UNG (uracil DNA glycosylase)
Diseases named in the same sentence as UNG in open-access papers (continued):
Sharing a sentence is not in itself a finding about the gene and the disease.
Sepsis (2 papers, 2014 to 2015). Sepsis is defined as life-threatening organ dysfunction caused by a dysregulated host response to infection. "Mito-Vit-E alleviated sepsis-induced reduction in mitochondria-localized DNA repair enzymes including DNA polymerase γ, AP endonuclease, 8-oxoguanine glycosylase, and uracil-DNA glycosylase." (PMID 26448624, 2015).
viral infection (2 papers, 2016 to 2021). "The activity of Family 1 uracil–DNA glycosylase (UNG) activity limits the efficiency of antimetabolite drugs and is essential for virulence in some bacterial and viral infections." (PMID 34771075, 2021). "Conversely, like known Vpr-target UNG, proteins in cluster #2 are downregulated early in viral infection, in the absence of Vif, and in the presence of reverse transcriptase inhibitors." (PMID 27690223, 2016).
acute myeloid leukemia (1 paper, 2018). Acute myeloid leukemia (AML) is a group of neoplasms arising from precursor cells committed to the myeloid cell-line differentiation. "In addition, there is an apparent upregulation in the expression of the UNG gene in some leukemias, as shown by gene expression profiling analysis of 170 acute myeloid leukemia (AML) patients." (PMID 30167090, 2018).
dentin caries (1 paper, 2018). "The highest gene expression was in dentin caries including for ADS, glycerol kinase, uracil-DNA glycosylase and urease." (PMID 30034639, 2018).
depression (1 paper, 2018). "Regarding the effect of combined genotypes, it was found that the T/T-A/A-G/C (DUT (rs4775748), SMUG1 c.-31A>G (rs3087404) and UNG (rs34259) carriers had an increased risk of depression, whereas the T/G-A/G-G/G carriers had a reduced risk." (PMID 29967751, 2018).
leishmaniasis (1 paper, 2018). Infectious disease that is transmitted through the bite of hematophagous female phlebotomine sand flies. "Added to this, association of UNG expression with resistance against commonly used antileishmanial drugs opens a new window of opportunity to target LdUNG for development of combination therapy against leishmaniasis." (PMID 29636843, 2018). "Our findings suggest that UNG could be a potential target for novel drugs against leishmaniasis." (PMID 29636843, 2018).
lymphopenia (1 paper, 2018). Reduction in the number of lymphocytes. "Because immunoglobulin dysregulation, CD4 lymphopenia and recurring infections persisted, targeted sequencing of the PID associated activation-induced cytidine deaminase (AID) and uracil DNA glycosylase (UNG) genes was carried out, but revealed no mutations." (PMID 30386345, 2018).
mental disorder (1 paper, 2018). A disease that has its basis in the disruption of mental process. "Table presents a distribution of combined genotypes of DUT rs4775748, SMUG rs3087404 and UNG rs34259 single-nucleotide polymorphisms, and OR with 95% CI in groups of patients with rDD and controls without mental disorders." (PMID 29967751, 2018). "Table presents a distribution of genotypes and alleles of DUT g.48346598G>T (rs4775748), SMUG1 c.-31A>G (rs3087404) and UNG g.7245G>C (rs34259) single-nucleotide polymorphisms, and OR with 95% CI in groups of patients with rDD and controls without mental disorders." (PMID 29967751, 2018).
Obesity (1 paper, 2023). Accumulation of substantial excess body fat. "In opposition to other reports, we only detected minor effects of AcG and UnG levels in response to an oral glucose intake (instead of profound declines) which were further attenuated with incrementing obesity." (PMID 37420007, 2023). "Our data supports the observation of a relative excess of AcG or lack of UnG in obesity." (PMID 37420007, 2023).
ocular toxoplasmosis (1 paper, 2022). Ocular toxoplasmosis is an infection in the eye caused by the parasite, Toxoplasm a gondii. "The aim of the present study was to assess detection rate of T. gondii DNA in blood samples of clinically diagnosed of ocular toxoplasmosis using uracil DNA glycosylase-supplemented loop-mediated isothermal amplification (UDG-LAMP) and real-time quantitative PCR (qPCR) based on REP-529 and B1." (PMID 35078413, 2022).
pancreatic adenocarcinoma (1 paper, 2018). "In pancreatic adenocarcinoma (PAAD) cell lines, both APOBEC3A and UNG expression was significantly negatively correlated (ρ ≤ − 0.819, padj ≤ 0.0001; n = 28 for APOBEC3A and 5 for UNG; Ntests = 26,610) with log(IC50) of the BET inhibitor JQ1." (PMID 29642934, 2018).
cancer (38 papers, 2008 to 2025). A tumor composed of atypical neoplastic, often pleomorphic cells that invade other tissues. "We found a relatively weak contribution of REV1 and UNG mutation or silencing to APOBEC mutagenesis in human cancers, which nevertheless confirms the expected trend: on average, samples defective for REV1 or UNG display an 8% decrease in C > G mutations." (PMID 32358516, 2020). "We demonstrate that IL-6 trans-activates the expression of APOBEC3B and trans-inactivates the expression of UNG, thus unbalancing APOBEC3B/UNG and facilitating cancer evolution and development." (PMID 36831487, 2023). "To directly assess the effect of UNG and SMUG1 on the generation of SBS2 and SBS13a/b in cancer cells, we expressed UNG–GFP in BC-1 cells, and CRISPR–Cas9 deleted SMUG1 from BT-474 cells and UNG from BT-474 and MDA-MB-453 cells." (PMID 35859169, 2022). "Inhibition of uracil DNA glycosylase also sensitizes cancer cells to 5-FdUrd similar to like dUTPase inhibition." (PMID 34068736, 2021). "Many cancers have developed resistance to 5-FU, due to removal by the enzyme uracil-DNA glycosylase (UDG), a type of base excision repair enzyme (BER) that can excise uracil and 5-fluorouracil (5-FU) from DNA." (PMID 34123270, 2020). "Five genes, UNG, SMUG1, MBD4, TDG, and DUT, are involved in the repair and prevention of uracil misincorporation into DNA, an anomaly that can lead to cancer-causing mutations." (PMID 30679536, 2019). "Our analysis of cancer cell line data identified associations of drug sensitivity with expression levels of APOBEC3A, APOBEC3B, REV1, and UNG genes and with abundance of sequence motifs and kataegis clusters attributed to APOBEC activity." (PMID 29642934, 2018). "One of the potential mechanisms is the removal of 5-FU by several DNA glycosylases, and the 5-FU removal by uracil DNA glycosylase (UDG) in cancer cells was also reported to be related to 5-FU resistance, and we will also be discussing one of the DNA repair processes, base excision repair (BER)." (PMID 39189649, 2024). "Additionally, the crucial role of UNG in DNA repair makes it a very promising pharmacological target in case of cancer therapy and also treatments against pathogens (including bacteria and viruses)." (PMID 34068736, 2021). "However, UNG-silencing in combination with DUTi significantly increased cancer cell lethality when used in combination with FUdR or epirubicin and significantly increased growth inhibition with DUTi in combination with FUdR." (PMID 33824328, 2021). "These significant increases in DNA damage and cancer cell lethality when UNG is silenced in combination with dUTPase inhibition indicate a clear role for uracil misincorporation in the increased levels of DNA damage and lethality when used in combination with either FUdR or epirubicin." (PMID 33824328, 2021). "Finally, depletion of UNG was recently shown to induce synthetic lethality in APOBEC3B overexpressing cancers." (PMID 32264925, 2020). "Alternatively, the underlying signature change may not be detectable due to REV1/UNG mutation occurring late in cancer development compared to APOBEC overactivation." (PMID 32358516, 2020).
cancer (continued). "Indeed, a lack of C > G mutations has been observed in a cancer cell line with UNG silencing." (PMID 32358516, 2020). "We observed a bimodal distribution of APOBEC3B expression and unimodal distributions of APOBEC3A, REV1, UNG, and FHIT in the pan-cancer dataset." (PMID 29642934, 2018). "Examination of gene expression measures in the pan-cancer dataset showed a bimodal distribution of APOBEC3B expression, whereas APOBEC3A, REV1, UNG, and FHIT had unimodal distributions of their expression measures." (PMID 29642934, 2018). "The efficiency of MutSα-directed repair of U•G is comparable to that of the UNG-directed pathway, and this may explain why, in humans, UNG-deficiency imparts compromised immunity but neither a decrease in genomic stability nor a broad predisposition to cancer." (PMID 18954457, 2008). "We and others have described how UNG protein depletion, or inhibition of its catalytic activity using the small UNG inhibitor protein (UGI), can significantly increase the potency of FdU or pemetrexed in human cancer cell lines." (PMID 40663394, 2025). "Starting with monofunctional glycosylases, UNG KO was the first example of cancer development without a carcinogen and increased incidence of B-cell lymphomas in old age." (PMID 37762489, 2023). "Finally, our data directly link uracil excision by UNG and REV1-dependent TLS to the acquisition of APOBEC3-induced signatures in human cancer cells." (PMID 35859169, 2022). "We identified six genes including UNG, FUCA2, DERA, GMFB, TF, and SNX24 as significantly downregulated and two genes including MYL9 and TAGLN as significantly upregulated upon mir-145 over-expression in distinct cancer types." (PMID 27655328, 2016). "UNG, FUCA2, DERA, GMFB, TF, and SNX24 as significantly downregulated upon mir-145 over-expression, are expected to have elevated expressions in tumor samples considering low levels of miR-145 in several cancer types." (PMID 27655328, 2016). "The expression of breast cancer 1, early onset (BRCA1), RAD51, bloom syndrome, RecQ helicase-like (BLM), flap-endonuclease 1 (FEN1), uracil-DNA glycosylase (UNG), damage-specific DNA binding protein 2 (DDB2) and exonuclease 1 (EXO1) were significantly suppressed after 24 h ZEA treatment." (PMID 24788721, 2014). "To address this question, we investigated the presence of APOBEC3B-like mutational patterns and mRNA expression of the APOBEC3A, APOBEC3B, UNG, REV1, and FHIT genes in cancer cell lines, in order to identify those cancer cell lines that may have experienced kataegis events." (PMID 29642934, 2018). "Whereas many studies have focused on the molecular roles of APOBEC3B, and to some extent APOBEC3A, possible cumulative effects of action of APOBEC3A, APOBEC3B, UNG, REV1, and FHIT on generation of APOBEC3B-like mutation motifs and on drug sensitivity in cancer have not been clearly elucidated." (PMID 29642934, 2018).
tumor (29 papers, 2012 to 2025). "Overexpressing the small UNG inhibitor protein (UGI) in mismatch repair–deficient (MMR-deficient) MC38 cells injected into C57BL/6J mice delayed tumor growth and prolonged survival when combined with FdU." (PMID 40663394, 2025). "Regions containing many mutations in the UNG/SMUG1-DKO tumours tended to have fewer exons, for example the region between 56–60 Mbp on chromosome 5 (grey region), perhaps indicating that BER has a global genome repair function." (PMID 28775312, 2017). "Some regions, such as between 115–127 Mbp on Chromosome 5 (purple region), were highly mutated in the MMR defective tumours, but had very low mutation loads in the UNG/SMUG1 tumours." (PMID 28775312, 2017). "Alternatively, intercrossing with more specific DNA damage response‐deficient mice, such as the UNG KO mouse, might be useful to see the accumulation of A3B‐induced mutations and tumor development." (PMID 40213992, 2025). "When MC38 mismatch repair–deficient (MMR-deficient) CRC cells were inoculated into C57BL/6J mice and UGI expression was induced to inhibit UNG activity, delayed tumor growth and prolonged survival were observed only when combined with FdU treatment." (PMID 40663394, 2025). "Depletion of CD8+ T lymphocytes ablates the tumor growth and survival benefits of UNG knockdown in the MC38 murine model." (PMID 40663394, 2025). "Depletion of UNG in CT-26 cells had only a small effect on tumor growth and survival in BALB/c mice, suggesting that the UNG-associated replication stress threshold in this cell line is higher than DDR-deficient MC38 cells." (PMID 40663394, 2025). "To do so, we coupled UDS with unique molecular identifier technology (UMI) to mitigate errors propagated by PCR, and with uracil-DNA glycosylase (UDG) treatment of tumor-derived DNA to mitigate errors induced by FFPE." (PMID 38321573, 2024). "Taken together, these findings suggest that subclonal A3B expression with TKI therapy in conjunction with UNG downregulation contributes to increased tumor growth and TKI resistance." (PMID 38049664, 2024). "Further studies are needed to address the mutation features in the FHIT-deficient pre-tumor lesion and tumor models with distinct levels of APOBEC3B and UNG." (PMID 36831487, 2023). "In some models, like the UNG knock-out mice, there was some spontaneous tumour formation but at low penetrance and late onset." (PMID 37373453, 2023). "Within the irradiated group, we found downregulation of UNG, FEN1, PARP3, POLD, NTLH1, ERCC1 and MPG which are linked to increased DSBs, sensitivity to alkylating agents, impaired tumor growth and reduced EMT, DSB repair and mitotic progression." (PMID 34680264, 2021).
tumor (continued). "Intriguingly, UNG has very recently been shown to improve B cell fitness and to have tumor-enabling activity possibly by protecting B cells from telomeric loss induced by AID." (PMID 33362210, 2020). "On the other, UNG protects B cells from telomeric loss mediated by AID, and this can in turn result in a tumor enabling activity by protecting cell fitness." (PMID 33362210, 2020). "Together, these results suggest that the interplay between AID and UNG is a delicate balance where expression levels, and possibly the stage of tumor progression, play a role." (PMID 33362210, 2020). "To assess the impact of the combined loss of UNG and SMUG1 activity on the spectrum of mutations generated in vivo, we subjected these tumours to whole genome sequencing." (PMID 28775312, 2017). "The overrepresentation of C > T transitions at CpG dinucleotides in UNG/SMUG1-DKO tumours was surprising as these are generally interpreted as resulting from 5-methylcytosine, which deamination product, thymidine, is not recognised by either SMUG1 or UNG." (PMID 28775312, 2017). "A key result in this study was that the MC38 MMR-deficient cell line showed a modest FdU-dependent sensitivity to UNG inhibition, while shRNA depletion of UNG was sufficient to bring about FdU-independent tumor clearance when MC38 cells were introduced into C57BL/6J mice." (PMID 40663394, 2025). "A3B and UNG expression levels were then examined in multiple human tumor xenograft models." (PMID 38049664, 2024). "The tumor mass in the xenograft models will be examined for apoptosis alternation such as caspase enzyme activity or DNA repair enzymes (such as Uracil-DNA glycosylase) and tested for the interaction of HPV oncoprotein and EGFR nuclear trafficking-related factors such as cyclin D1." (PMID 36358752, 2022). "Time-dependent increased RAD51, FEN1 and UNG expression levels were confirmed after LPS stimulation, which may contribute to tumor cell fitness." (PMID 33446690, 2021). "UNG has an important role in replication fork stability independent of its catalytic activity, which may explain why depletion alone is sufficient to promote tumor clearance in the MC38 mouse model and is synergistic with aPD1 in CT-26 cells." (PMID 40663394, 2025). "The fact that C to T transition mutations were the dominating class of mutation found in the two UNG/SMUG1-deficient tumours showed that neither the other UDGs nor the MMR pathway are able to fully compensate for the loss of UNG and SMUG1 in U:G repair at CpG dinucleotides." (PMID 28775312, 2017). "The expression levels of three writers (DNMT1, DNMT3A, DNMT3B), two erasers (TET1, TET3), and eight readers (MBD4, ZBTB33, UHRF1, UHRF2, UNG, TDG, NTHL1, SMUG1) were dramatically higher in tumor tissues (p < 0.05)." (PMID 38317133, 2024). "Further investigation illustrated that DNMT1/3A/3B, TDG, SMUG1, UNG, NEIL1, MDB3/4, ZBTB33, and UHRF1/2 were essentially upregulated in tumor samples, while TET2, MBD1, and MBD2 were downregulated in tumor samples." (PMID 35205097, 2022). "In contrast with UNG inhibition, UNG depletion alone showed a significant effect on tumor growth and the addition of FdU had no further benefit." (PMID 40663394, 2025). "In contrast, depletion of UNG in MMR-competent CT-26 cells had no statistically significant benefit on tumor growth or survival in the BALB/c mouse strain." (PMID 40663394, 2025). "The DNA repair activity of multiple lesion-specific DNA glycosylases, such as MPG, SMUG1, UNG, NTH1, NEIL1 and OGG1 could be readily detected in lysates from human tumor cells (LN428, U2OS and K562 cell lines) and normal cells (PBMCs)." (PMID 30167090, 2018).
tumor (continued). "Unfortunately, we cannot separate the relative roles of UNG and SMUG1 in mutation avoidance because neither of our single knockout mice developed tumours under SPF conditions." (PMID 28775312, 2017). "Thus, the antitumor phenotypes resulting from UNG inhibition or protein depletion arise from changes that promote immune activation in mice, rather than induced tumor cell toxicity." (PMID 40663394, 2025). "Interestingly, C > A and C > G mutations did not retain the NpCpG context bias as was observed in the UNG/SMUG1-DKO tumours, but was instead occurring mostly in NpCpT contexts." (PMID 28775312, 2017). "As the sequence artefacts detected in the FFPE tumour DNAs were almost exclusively C:G>T:A base substitutions (16/17), we reasoned that the C:G>T:A sequence artefacts could be eliminated by treating FFPE DNA with uracil-DNA glycosylase (UDG)." (PMID 22643842, 2012).